EZH2 (enhancer of zeste 2 polycomb repressive complex 2 subunit)
Diseases named in the same sentence as EZH2 in open-access papers (continued):
Sharing a sentence is not in itself a finding about the gene and the disease.
T-cell neoplasms (3 papers, 2023 to 2024). "These gain-of-function mutations observed in other B- and T-cell neoplasms confer increased sensitivity to EZH2 inhibition and warrant further study in T-PLL." (PMID 37569479, 2023). "Therefore, it is possible that two or three of these signaling pathways could be associated with EZH2 upregulation in these T-cell neoplasms." (PMID 38339397, 2024). "In the other T-cell neoplasms, there was a variable, but higher, co-expression of EZH2 with pERK, MYC, and pSTAT3." (PMID 38339397, 2024). "Our findings are consistent with previous cohort studies that reported EZH2 overexpression in the T-cell neoplasms." (PMID 38339397, 2024). "In the other T-cell neoplasms we examined, a high prevalence of EZH2 upregulation was detected in most of the T-cell neoplasms except in T-PLL." (PMID 38339397, 2024). "In other T-cell neoplasms, a high prevalence of EZH2 overexpression was identified (86%), except for T-PLL (33%)." (PMID 38339397, 2024). "In T-cell neoplasms, a previous study showed that EZH2 expression was correlated with the expression of MYC and/or pSTAT3 in a subset of T-cell neoplasms." (PMID 38339397, 2024). "EZH2 is overexpressed in several tumor entities including T-cell neoplasms leading to epigenetic and consecutive oncogenic dysregulation." (PMID 37297005, 2023). "In addition, to understand the signaling pathway involved in EZH2 activation in ATLL and other T-cell neoplasms, we studied the intracellular signaling cascade-associated molecules, pERK1/2, CMYC, and pSTAT3, in relation to EZH2 expression." (PMID 38339397, 2024). "The widespread overexpression of EZH2 in these T-cell neoplasms suggests that EZH2 could function as an oncogenic protein in T-cell tumorigenesis." (PMID 38339397, 2024). "Additionally, EZH2 is overexpressed in most T-cell neoplasms, suggesting that EZH2 could function as an oncogenic protein in T-cell tumorigenesis." (PMID 38339397, 2024). "In this study, EZH2 was overexpressed in all ATLL cases and in the majority of other T-cell neoplasms we examined, except T-PLL." (PMID 38339397, 2024). "Immunohistochemical staining (IHC) was performed for EZH2, pERK, MYC, and pSTAT3 on 43 ATLL cases and 104 cases of other T-cell neoplasms." (PMID 38339397, 2024). "Here, we investigated EZH2 expression and potential signaling molecules that correlate with EZH2 expression in ATLL and other T-cell neoplasms." (PMID 38339397, 2024). "Different from the other types of T-cell neoplasms, in T-PLL, only a small percentage of cases showed EZH2 overexpression (3/9, 33%)." (PMID 38339397, 2024). "Our study demonstrated that EZH2 could be a potential therapeutic target for ATLL and some other T-cell neoplasms." (PMID 38339397, 2024). "In case studies, EZH2 overexpression has been reported in ATLL and a range of T-cell neoplasms." (PMID 38339397, 2024).
type 2 diabetes (3 papers, 2021 to 2025). "Therefore, our study contributes to a better understanding of the sex-dependent influence on EZH2 and H3K27me3 levels in renal tubules of non-diabetic and db/db mice, a model of type 2 diabetes." (PMID 41227374, 2025).
VEXAS syndrome (3 papers, 2024 to 2026). An adult-onset inflammatory disease that affects only males and is caused by somatic, not germline, mutations. "Subsequent NGS examination identified a mutation in the EZH2 gene with unclear significance and a UBA1 mutation, leading to a diagnosis of very low-risk MDS (IPSS-R of 1) and VEXAS syndrome." (PMID 38398362, 2024).
acute monocytic leukemia (2 papers, 2021 to 2022). Acute monoblastic leukemia (AML-M5), is one of the most common subtypes of acute myeloid leukemia (AML) that is either comprised of more than 80% of monoblasts (AML-M5a) or 30-80% monoblasts with (pro)monocytic differentiation (AML-M5b). "EZH2 is overexpressed in pediatric acute monocytic leukemia and the GSK126, UNC1999 and EPZ-5687 inhibitors suppresses the EZH2 activity on H3K27 leading to a reduction of proliferation and increased apoptosis." (PMID 36011043, 2022).
allergic rhinitis (2 papers, 2017 to 2021). Inflammation of the nasal mucous membranes caused by an IgE-mediated response to external allergens. "GAS5 suppresses Th1 differentiation and promotes Th2 differentiation via EZH2 inhibition, thus eliciting the development of allergic rhinitis." (PMID 34781960, 2021). "We measured the expression of Ezh2 in Th1 and Th2 cells in peripheral blood mononuclear cells after acute challenge with house dust mite using flow cytometry in patients with allergic rhinitis (AR) and controls." (PMID 28740493, 2017). "Adjusted odds ratios of allergic rhinitis related to enhancer of zeste homolog 2 (Ezh2) expression." (PMID 28740493, 2017). "Odds ratios of allergic rhinitis related to enhancer of zeste homolog 2 (Ezh2) expression." (PMID 28740493, 2017).
Alzheimer disease (2 papers, 2021 to 2025). A progressive, neurodegenerative disease characterized by loss of function and death of nerve cells in several areas of the brain leading to loss of cognitive function such as memory and language. "EZH2 hyperactivation was also observed in other models of neurodegeneration such as the ataxia-telangiectasia mouse and in susceptible neurons of mouse models of Alzheimer’s disease." (PMID 34502238, 2021). "Although mainly disruptive, there is evidence that EZH2 may also be involved in the maintenance of the BBB integrity, at the early stages of Alzheimer’s disease through regulation of genes implicated in BBB development and maintenance." (PMID 40723311, 2025).
ameloblastoma (2 papers, 2021 to 2024). The most common odontogenic tumor, arising from the epithelial component of the embryonic tooth and usually affecting the molar-ramus region of the mandible or maxilla. "Of note, we found that CC ameloblastoma cells were endowed with stemness and contributed to tumor recurrence, which was dominated by the EZH2-mediated program." (PMID 38424060, 2024). "Targeting EZH2 effectively eliminated CC ameloblastoma cells and inhibited tumor growth in ameloblastoma patient-derived organoids." (PMID 38424060, 2024). "The authors concluded that, according to the location of immunopositive cells, Mel-18 and Ezh2 might be involved in the growth of odontogenic keratocysts, and almost all PcG proteins are possibly associated with cell proliferation and differentiation of ameloblastomas." (PMID 33680332, 2021). "The presence of patterns of five human PcG proteins (Bmi-1, Ring1b, Mel-18, Ezh2, and Suz12) in ameloblastomas and odontogenic keratocysts was previously analyzed." (PMID 33680332, 2021).
angioimmunoblastic T-cell lymphoma (2 papers, 2024 to 2025). A mature T-cell non-Hodgkin lymphoma, characterized by systemic disease and a polymorphous infiltrate involving lymph nodes and extranodal sites. "We subsequently evaluated 16 patients with angioimmunoblastic T cell lymphoma (AITL) who received the CHOPE regimen at Peking University Cancer Hospital and found that individuals with elevated EZH2 expression exhibited reduced progression-free survival (PFS)." (PMID 40659662, 2025).
Anterior polar cataract (2 papers, 2018 to 2022). "Furthermore, the phosphorylation status and gene expression modulation of EZH2 are implicated in control of anterior subcapsular cataracts (ASC) in human and mouse eyes." (PMID 35293697, 2022). "Our data showed that the expression levels of EZH2 mRNA are increased in human PCO attached LECs and LECs obtained from patients with anterior polar cataracts, which indicated that EZH2 was involved in the development of PCO." (PMID 29977916, 2018). "Furthermore, upregulation of MYC mRNA and EZH2 mRNA was detected in the LECs obtained from patients with anterior polar cataracts compared with patients with nuclear cataracts." (PMID 29977916, 2018). "It has been shown that Myc and EZH2 are overexpressed in human PCO attached LECs and LECs obtained from patients with anterior polar cataracts, indicating that MYC and EZH2 were involved in the development of PCO." (PMID 29977916, 2018).
Ataxia (2 papers, 2017 to 2021). Ataxia refers to impaired coordination of voluntary muscle movement. "In the ataxia-telangiectasia mouse model, the delivery of a lentiviral vector coding for a shRNA against EZH2 into the cerebellum protects the Purkinje neurons from degeneration." (PMID 34502238, 2021). "Considering these studies, our results support the idea that abnormalities in EZH2 expression inside the cerebellum or metencephalon could be a contributing factor for the development of neurological disorders such as ataxia and autism spectrum disorder." (PMID 28720872, 2017).
autism spectrum disorder (2 papers, 2017 to 2025). A spectrum of developmental disorders that includes autism, and Asperger syndrome. "Our results suggest that EZH2 is involved in regulating ZIC2 and SHANK1 which have been linked to neurological diseases such as autism spectrum disorder." (PMID 28720872, 2017).
bacteremia (2 papers, 2021 to 2023). "In CLP alone, the Ezh2 inhibitor attenuated kidney damage (serum creatinine) and serum cytokines (TNF-α, IL-6, and IL-10) but not cell-free DNA, endotoxemia, and bacteremia." (PMID 37239864, 2023).
benign salivary gland tumors (2 papers, 2015 to 2024). "In benign salivary gland tumors, the role of EZH2 as a tool to show malignant transformation deserves investigation." (PMID 38477804, 2024). "EZH2 expression was investigated in 54 malignant and 40 benign salivary gland tumors of various histological types by standard immunohistochemistry." (PMID 26377323, 2015). "All 40 benign salivary gland tumors investigated were negative for EZH2, while 52 of the 54 malignant tumors proved to be positive." (PMID 26377323, 2015).
breast ductal carcinoma (2 papers, 2020 to 2024). "Using the affinity-purified K20me antibodies, we examined K20 methylation of EZH2 in human breast ductal carcinoma T47D cells, as this cell line was previously used to analyze the effect of AKT-mediated serine phosphorylation in EZH2." (PMID 38346162, 2024).
Camptodactyly (2 papers, 2023 to 2025). The distal interphalangeal joint and/or the proximal interphalangeal joint of the fingers or toes cannot be extended to 180 degrees by either active or passive extension. "This study reports a novel EZH2 variant associated with atypical manifestations, including severe bilateral camptodactyly and complex brain malformations." (PMID 41300605, 2025).
carcinoid (2 papers, 2022 to 2023). "EZH2 immunoreactivity has also been reported in thymic neuroendocrine neoplasms, with one study showing >25% EZH2 staining in 83% (5/6) of thymic large cell neuroendocrine carcinomas and 0/5 carcinoid tumors, and a separate study reporting >1% EZH2 staining in 37% (10/27) of thymic carcinoid tumors." (PMID 37190202, 2023).
Cardiac ischemia (2 papers, 2019 to 2025). "In the current study we provide novel evidence suggesting that cardiac ischemia triggers its epigenetic regulation via promoter hypermethylation and EZH2-mediated suppression." (PMID 30089854, 2019). "Cardiac ischemia also correlates with induction of EZH2, an epigenetic regulator that may coordinate with differential DNA methylation to suppress KLF15 and other downstream metabolic gene targets." (PMID 30089854, 2019).
cervical (2 papers, 2016 to 2025). "To further investigate the role of EZH2 in cervical carcinogenesis, we employed CRISPR/Cas9 technology targeting exon 2 of EZH2 and identified genetic interruption and significant down-regulation of the EZH2 protein in HeLa and SiHa cell lines (Figure 2A1)." (PMID 27092879, 2016).
Chronic colitis (2 papers, 2024 to 2025). A chronic inflammatory disease of the large intestine (colon, cecum and rectum). "Rectal insulin instillation promoted EZH2 expression and EZH2 inhibition alleviated chronic colitis." (PMID 38243324, 2024). "Here, we defined that the INSR of intestinal mucosal T-cells could promote intestinal TRM differentiation via EZH2 and exacerbate chronic colitis." (PMID 38243324, 2024).
chronic liver failure (2 papers, 2018 to 2020). Liver failure that develops slowly and gradually for some time, possibly for years, often as the result of cirrhosis, or malnutrition. "In previous research, it was shown that EZH2-catalyzed H3K27 trimethylation plays a key role in acute-on-chronic liver failure via a TNF-mediated pathway." (PMID 33262329, 2020).
clear cell carcinoma (2 papers, 2010 to 2020). "Our findings concerning the prognostic value of EZH2 in RCC, are in contrast to a recent study of 119 clear cell carcinoma patients, who reported that high tumor EZH2 levels indicate less aggressive tumor phenotypes with a favorable prognosis, as assessed by real-time RT-PCR." (PMID 20920340, 2010).
colon adenoma (2 papers, 2011 to 2020). An adenoma that arises from the colon. "We also found that the EZH2 expression levels were reduced in the human colon adenoma tissue samples compared to those in the normal colon tissue samples." (PMID 33390926, 2020).
cyst (2 papers, 2017 to 2025). A sac-like closed membranous structure that may be empty or contain fluid or amorphous material. "Thus, a decrease in the levels of EZH2-associated lncRNAs may interfere with the activity of this methyltransferase and act as an additional factor that downregulates cell proliferation and, by extension, cyst growth." (PMID 40243914, 2025).
diabetic neuropathy (2 papers, 2021 to 2025). A chronic, pathological complication associated with diabetes mellitus, where nerve damages are incurred due to diabetic microvascular injury involving small blood vessels that supply these nerves, resulting in peripheral and/or autonomic nerve dysfunction. "This research systematically explores for the first time the role of circ_0012856 in regulating autophagy through EZH2, highlighting the importance of autophagy in diabetic neuropathy." (PMID 40520073, 2025).
embryonal carcinoma (2 papers, 2014 to 2023). A non-seminomatous malignant germ cell tumor characterized by the presence of large germ cells with abundant cytoplasm resembling epithelial cells, geographic necrosis, high mitotic activity, and pseudoglandular and pseudopapillary structures formation. "On the other hand, naturally elevated expression of miR-124 in embryonic carcinoma cells undergoing neuronal differentiation correlated with down-regulation of Ezh2 levels." (PMID 24878960, 2014). "To examine whether physiological levels of miR-124 could regulate Ezh2 expression during neuronal differentiation, we took advantage of the retinoic acid (RA)-induced P19 embryonic carcinoma in vitro differentiation model." (PMID 24878960, 2014).
epithelial ovarian tumors (2 papers, 2021 to 2022). "The patients with ovarian epithelial tumors had the second-highest alteration frequency of EZH2 (<8%) with the “amplification” type as the primary type." (PMID 34381492, 2021).
Fanconi anemia (2 papers, 2025). Fanconi anemia (FA) is a hereditary DNA repair disorder characterized by progressive pancytopenia with bone marrow failure, variable congenital malformations and predisposition to develop hematological or solid tumors. "Functional enrichment analysis revealed that genes associated with EZH2 were markedly enriched in pathways related to the cell cycle, DNA replication, and Fanconi anemia repair, all of which strongly connect with regulating circadian rhythms." (PMID 41298718, 2025).
gall bladder carcinoma (2 papers, 2020 to 2022). "Previous studies have reported that lncRNA MEG3 promotes the ubiquitination of EZH2 and inhibits the proliferation and invasion of gallbladder carcinoma cells by regulating LATS224." (PMID 32157157, 2020). "In gall bladder carcinoma (GBC), EZH2 and COX-2 were chosen as biomarkers and considered future targets in GBC therapy." (PMID 36471782, 2022).
gastritis (2 papers, 2021 to 2024). Inflammation of the stomach. "DNMT-1/3A/3B and EZH2 expression were significantly upregulated in Hp-associated gastritis and carcinomas." (PMID 38542354, 2024).
granulosa cell tumor (2 papers, 2017 to 2018). A slow-growing, malignant tumor, characterize by the presence of granulosa-like cells and Call-Exner bodies, that is almost always found in the ovary. "The epigenetic dysregulation of central granulosa cell factors such as FOXL2 are involved in the development of granulosa cell tumors, which is possible through EZH2 interaction." (PMID 30087896, 2018). "Interestingly, the promoter of the FOXL2 gene was found to be hypermethylated in ovary granulosa cell tumors concomitant with increased EZH2 expression." (PMID 28209164, 2017).
Hypercalcemia (2 papers, 2021 to 2022). An abnormally increased calcium concentration in the blood. "Data obtained in our study demonstrated that silencing of Drp1 exerted inhibitory properties in mitochondrial fragmentation to attenuate hypercalcemia-induced neurological impairment in CKD through the inactivation of ROS/HIF-1α/EZH2 axis." (PMID 36050772, 2022). "Silencing OGT reduced the hypercalcemia-induced toxicity of neurons by inhibiting the expression of EZH2, which elevated the expression of CXCL1 in primary neurons by diminishing KLF2." (PMID 34462420, 2021). "Silencing OGT attenuated hypercalcemia-induced neurotoxicity by regulating the EZH2/KLF2/CXCL1 axis." (PMID 34462420, 2021). "Next, OGT silencing and CXCL1 overexpression were performed simultaneously in hypercalcemia-treated mouse neurons to further verify the effect of the OGT/EZH2/KLF2/CXCL1 axis on hypercalcemia-induced neurotoxicity." (PMID 34462420, 2021). "Initially, we found in this study that downregulation of OGT reduced the toxicity of primary neurons induced by hypercalcemia by inhibiting the expression of EZH2." (PMID 34462420, 2021). "However, the interactions among Drp1, ROS, HIF-1α, EZH2, as well as their involvement in mitochondrial fragmentation and hypercalcemia-induced neuronal injury in the progression of CKD need to be explored more deeply." (PMID 36050772, 2022). "At last, CKD mice were injected with the corresponding AAV (sh-NC + Vector, sh-Drp1 + Vector, and sh-Drp1 + EZH2) to explore whether Drp1 could regulate the ROS/HIF-1α/EZH2 axis to alleviate neurological impairment induced by hypercalcemia in CKD." (PMID 36050772, 2022). "Moreover, the obtained data in the present study identified that Drp1 could promote HIF-1α binding to EZH2 promoter by inducing ROS production, which might be one of mechanisms responsible for aggravated neuronal injury induced by hypercalcemia in CKD mice." (PMID 36050772, 2022). "Hereby, it was inferred that OGT might mediate EZH2 in primary neurons induced by hypercalcemia." (PMID 34462420, 2021). "Our mechanistic study further revealed that EZH2 could promote the expression of CXCL1 in primary neurons by inhibiting KLF2, thereby promoting the toxicity of primary neurons induced by hypercalcemia." (PMID 34462420, 2021). "In order to verify our hypothesis on whether EZH2 promoted CXCL1 expression in primary neurons by downregulating KLF2, we first detected the protein expression of KLF2 and CXCL1 in brain tissues and hypercalcemia-induced neurons of CKD mice." (PMID 34462420, 2021).
hyperparathyroidism (2 papers, 2019 to 2021). Hyperfunction of the parathyroid glands resulting in the overproduction of parathyroid hormone. "This discovery also provides a novel interpretational key for the finding of Ezh2 activating mutations in hyperparathyroidism and parathyroid cancer." (PMID 33608392, 2021). "Interestingly, EZH2 is activated in human parathyroid malignancies and in hyperparathyroidism, suggesting that the gene has a major role in the transcriptional program of this gland." (PMID 33608392, 2021).